FOXA1 (forkhead box A1)
Diseases named in the same sentence as FOXA1 in open-access papers (continued):
Sharing a sentence is not in itself a finding about the gene and the disease.
breast carcinoma (continued). "Given the association between HER2 status and the resistance to endocrine treatments, we initially analyzed FOXA1 chromatin interactions in breast cancer cells with varying levels of HER2." (PMID 41224124, 2025). "First, we examined the impact of HER2 inhibition on the acetylation of FOXA1 in ER+ breast cancer cell lines with high HER2 levels (BT474 and MCF-7–HER2)." (PMID 41224124, 2025). "In breast cancer, we observed that the lead variants were significantly enriched in the TFs ESR1 (n = 73 genes), followed by TCF7L2 (n = 13) and FOXA1 (n = 11) (Fisher’s exact test, P < 0.01 for all)." (PMID 39535029, 2025). "We have previously shown that the AR and FOXA1 cistromes demonstrate an extraordinary overlap in MDA-MB-453 cells and that FOXA1 is required for AR to regulate genes that define the molecular apocrine breast cancer phenotype." (PMID 38317241, 2024). "This modification of FOXA1 promotes breast cancer metastasis by setting up the transcription of numerous metastasis regulators." (PMID 39684874, 2024). "Another upregulated gene, FOXA1, a multi-faceted transcriptional regulator, is an established marker of a good prognosis in luminal breast cancer." (PMID 38999963, 2024). "FOXA1 or FOXA2 triggers lipid metabolism reprogramming by maintaining high expression of endothelial lipase (LIPG) in breast cancer, allowing breast cancer cells to grow and extracellular lipids required for proliferation." (PMID 38605023, 2024). "We have delineated the core, conserved function of FOXC1 in TNBC, and show that these core sites are parallelly regulated by FOXA1 in ER+ breast cancer." (PMID 39171293, 2024). "We found poorer overall survival for high vs. low FOXA1 gene expression amongst patients with any breast cancer subtype (n = 2976) as well as with HR+ breast cancer (n = 2005) specifically." (PMID 39000600, 2024). "Most GATA3/FOXA1 studies, mostly focusing on breast cancer, demonstrated that the combination of the two indicators can better predict the prognosis than either indicator alone." (PMID 38425344, 2024). "O-GlcNAcylation of FOXA1 reasseminates FOXA1 binding to chromatin to promote breast cancer metastasis by coordinating the transcription of many pro-cancer cell metastasis regulators." (PMID 38605023, 2024). "In ER-positive breast cancer, FOAX1 is an oncogene, whereas in basal breast cancer, the role of FOXA1 is determined by ESR1." (PMID 38605023, 2024). "From a clinical point of view, the use of HIF-2a antagonists can reduce the proliferation, migration, and invasion of endocrine-resistant breast cancer cells with high FOXA1 expression." (PMID 38605023, 2024). "Studies have shown that FOXA1 expression is increased in endocrine therapy-resistant breast cancer, and FOXA1 is involved in the formation of drug resistance by regulating downstream gene expression through transcriptional reprogramming." (PMID 38605023, 2024). "Mechanistically, O-GlcNAcylation of FOXA1 reassembles the binding of FOXA1 to chromatin and promotes breast cancer metastasis by orchestrating the transcription of a number of metastatic regulators." (PMID 38605023, 2024). "For instance, a recent systematic review identified several promising methylation biomarkers, including APC, RASSFI, and FOXA1, which show strong potential for early breast cancer detection in non-invasive assays." (PMID 39456897, 2024). "We found that metformin decreases tumor growth in HR+ breast cancer through the downregulation of FOXA1." (PMID 39000600, 2024). "In the clinical database results, we checked the high expression of FOXA1 in only the hormone-receptor-positive breast cancer (HR+ BC) subtype and the worse overall survival for high FOXA1 gene expression in ER + /PR+ breast cancer patients." (PMID 39000600, 2024).
breast carcinoma (continued). "For instance, GREB1 is a key regulatory factor of the estrogen receptor, influencing chromatin accessibility through interactions with PRC1.2, ERα, and FOXA1, with FOXA1 being a notable biomarker for the luminal breast cancer subtype." (PMID 39452108, 2024). "In breast carcinoma, overexpression of FOXA1 is a good prognosis marker in ER+ breast carcinoma, but in prostate, epithelial ovarian, and gastric cancers, it indicates poor prognosis." (PMID 39337467, 2024). "Over 95% of oestrogen regulated genes require FOXA1 for oestrogen regulation in MCF-7 breast cancer cells." (PMID 38280856, 2024). "Several papers suggest the role of FOXA1 in various cancers, such as breast cancer, acute myeloid leukemia (AML), esophageal cancer, lung cancer, pancreatic cancer, and thyroid cancer." (PMID 39000600, 2024). "Overexpression of FOXA1 promoted the proliferation, migration, and invasion of breast cancer cells; thus, the antitumor effect of miR-100 in breast cancer was reversed after FOXA1 overexpression." (PMID 38605023, 2024). "FOXA1-mediated transcriptional reprogramming not only leads to endocrine resistance to breast cancer but also leads to bortezomib (BTZ) resistance to breast cancer." (PMID 38605023, 2024). "In conclusion, the expression of IL6 and IL8 was significantly increased in TAM-R cells, and FOXA1 affected the endocrine resistance of breast cancer by targeting the downstream factor IL6/8." (PMID 38605023, 2024). "Here, we advocate the use of small molecule blockade of FOXA1/ER transcriptional reprogramming in combination with endocrine therapy to address drug resistance in breast cancer." (PMID 38605023, 2024). "FOXA1 overexpression led to increased expression of E-cadherin, which reduced the metastasis potential of breast cancer cells." (PMID 38605023, 2024). "FOXA1 and ER expression are positively correlated in breast cancer, and the vast majority of ER-conducting signals require FOXA1 binding to chromatin for activation, leading to complete suppression of ER transcriptional activity when FOXA1 is absent." (PMID 38605023, 2024). "Specifically, in breast cancer, FOXA1 was reported to regulate the ERα function in hormone-receptor-positive breast cancer (HR+ BC), but the exact mechanism is unclear." (PMID 39000600, 2024). "While previous studies exploring the role of GATA3/FOXA1 focused mostly on breast cancer, there were limited studies on urothelial carcinoma, especially UTUC." (PMID 38425344, 2024). "Liu’s group concluded that O-GlcNAcylation of FOXA1 increases the metastatic capacity of breast cancer cells." (PMID 38605023, 2024). "In summary, our study provides insight into the epigenetic heterogeneity in breast cancer cell lines as well as the roles of FOXA1 and GRHL2 in shaping breast cancer properties." (PMID 38429368, 2024). "miR-204 inhibits breast cancer progression by targeting multiple genes involved in tumor progression such as FOXA1, AP1S3, RIOK1, RRM2, and PRMT5." (PMID 39199587, 2024). "This has strong analogies to the situation with ER in FOXA1-dependent breast cancer where only a subset of ER-expressing tumors depends on ER for survival." (PMID 37691854, 2023). "For example, the chromosomal loops on chr11 are complemented by the binding of CTCF, FOXA1, and ESRRA, molecules with potential roles in breast cancer risk." (PMID 37541849, 2023). "As an example, FOXA1 was found enriched in breast cancer type-specific GRNs, and several target genes were identified in colon cancer relative to normal cells." (PMID 37627195, 2023). "FOXA1 induces enhancer reprogramming and transcriptional activation of pro-metastatic oncogenes in endocrine-resistant breast cancer cells." (PMID 38135679, 2023). "FOXA1, a master transcriptional regulator, has been found to be overexpressed in luminal A and luminal B breast cancer subtypes, indicating its significant role in subtype-specific gene expression patterns." (PMID 37627195, 2023).
breast carcinoma (continued). "FOXA1 is a determinant of drug resistance in breast cancer cells, and it has different functions in response to treatment in ER+ and TNBC cell lines." (PMID 37715225, 2023). "By targeting FOXA1, miR-100 suppressed the migration, invasion, and proliferation of breast cancer cells." (PMID 37508580, 2023). "In both univariate and multivariate analyses, statistical interaction between AGR2 and FOXA1 on the PFS was significant (all P < 0.05) based on every cutoff point for ER-positive breast cancer." (PMID 37568077, 2023). "A Kaplan–Meier plot was used to test the FOXA1 regulation effect on the survival rate of all breast cancer patients (n = 2976)." (PMID 36836779, 2023). "Considering that there were interplays between them depending on ER status, we aimed to assess the statistical interaction between AGR2 and FOXA1 on breast cancer prognosis and examine the prognostic role of the combination of them by ER status." (PMID 37568077, 2023). "In breast cancer cells, FOXA1 and DSCAM-AS1 form a positive feedback loop to promote cancer cell proliferation." (PMID 36672150, 2023). "Previous studies showed that the expression of AGR2 in breast cancer cells required the transcription factor FOXA1." (PMID 37568077, 2023). "The prognostic role of either forkhead box A1 (FOXA1) or anterior gradient 2 (AGR2) in breast cancer has been found separately." (PMID 37568077, 2023). "FOXA1 is a transcriptional factor that plays an important role in hormone signaling in both breast cancer and normal breast tissues." (PMID 36836779, 2023). "In luminal breast cancer, there is a link between the number of carcinogenic stem cells (CSCs) and FOXA1 expression (BC)." (PMID 37626655, 2023). "AGR2 and FOXA1 expression in tumor tissues were evaluated with tissue microarrays by immunohistochemistry in 915 breast cancer patients with follow up data." (PMID 37568077, 2023). "The oncogenic transcription factor FOXA1 is hyperactive in metastatic endocrine-resistant breast cancer cells due to gene amplification or overexpression." (PMID 38135679, 2023). "ER+ breast cancer cell lines depend specifically on transcription factors FOXA1 and GATA3, which are overexpressed in ER+ breast carcinomas." (PMID 36727483, 2023). "In breast cancer, Foxa1 promotes breast cancer cell growth through the oestrogen-ERα signalling axis." (PMID 37752418, 2023). "For example, in breast cancer, abnormal upregulation of the luminal-lineage TF FOXA1 modifies genome-wide enhancer activity and induces transcriptional reprogramming to establish an endocrine-resistant state in metastatic tumors." (PMID 37234983, 2023). "In contrast, somatic mutations in the FOXA1 gene robustly associated with decreased patient survival in both our and TCGA-Broad GDAC breast cancer cohort." (PMID 37902422, 2023). "The FOXA1 transcription factor is a key regulator of breast cancer identity, as it controls ER activity." (PMID 38020889, 2023). "On the other hand, the difference in FOXA1 expression is statistically significant in ER+/PR+ breast cancer." (PMID 36836779, 2023). "Expression of FOXA1 is a promising predictive biomarker for tamoxifen effect in ER+/HER2− premenopausal breast cancer." (PMID 37773134, 2023). "The present review focuses on the function of the forkhead protein FOXA1 in breast cancer (BC) in relation to steroid hormone receptors." (PMID 36230619, 2022). "In breast cancer, it has been shown that the cooperative action between GATA3 and its cofactors Estrogen Receptor alpha (ER-α) and FOXA1 is important for the luminal breast cancer characterization." (PMID 35154280, 2022). "FOXA1 is a key transcription factor in breast cancer that can activate estrogen receptor (ER)-dependent genes and promote the proliferation of breast cancer." (PMID 36015212, 2022). "FOXA1 and H3K27ac play important role in the epigenetic regulation of breast cancer, including tamoxifen resistance." (PMID 36204307, 2022).
breast carcinoma (continued). "We predict transcription factors known to be involved in cancer as well as novel candidates to drive hypo-methylated regions such as FOXA1 and GATA3 in breast cancer, FOXA1 and TWIST1 in prostate cancer and NFE2L2 in lung cancer." (PMID 35331302, 2022). "Compared with HER2+ and HR+ breast cancers, FOXA1 was lowly expressed in TBNC, while FOXC1, FOXK2, and FOXM1 were highly expressed." (PMID 36292640, 2022). "As well FOXA1 proteins enhance hormone-driven ER activity and binding to intergenic regions of DNA in ER + breast cancer." (PMID 35906698, 2022). "To calculate the signature score, we used a gene list of breast cancer-specific FOXA1 or ER targets with positive expression correlations of each TF and its target genes as well as a regulatory potential of ≥0.5 in Cistrome Cancer33." (PMID 35676392, 2022). "FOXA1, which plays an important role in ER-dependent breast cancer, promotes the loading of ERα transcription factors to a subset of their binding sites." (PMID 35453496, 2022). "Worthy of note, FOXA1 is an interacting partner of both the estrogen and androgen receptor, playing a crucial role in the development and progression of breast cancer." (PMID 36230619, 2022). "FOXA1 suppresses the basal phenotype of breast cancer cells and is required for AR binding to target genes promoting breast cancer cell growth and proliferation." (PMID 36171192, 2022). "FOXA1 is a driver of luminal breast cancer identity, and a crucial pioneer and cooperating factor for nuclear receptor activity." (PMID 35774123, 2022). "Telaprevir prevents the growth of breast cancer cell lines by interfering with the IGF‐1R pathway leading to FOXA1 down‐regulation, ERα inhibition, and induction of apoptotic cell death." (PMID 36056637, 2022). "High frequencies of KMT2C and KMT2D mutations also downregulate ERα and FOXA1 expression, suggesting that the loss of KMT2C/D can reduce the sensitivity of luminal breast cancer to ER inhibitors by activating the hormone-independent pathway." (PMID 35453496, 2022). "Subsequently, DEMETER2 score comparisons were made in relation to gene expression in different molecular subtypes of breast cancer and we found that FOXA1 is up-regulated and is an essential gene in luminal ER+ breast cancer cells." (PMID 36359853, 2022). "In this study, we identified CA12 as one of the ERα target genes whose RNA expression is most correlated with that of ESR1, GATA3 and FOXA1 in breast cancer datasets." (PMID 36358871, 2022). "We next sought to determine if FOXA1 and GATA3 are causally involved in driving hypo-methylation in HCC1954 breast cancer cells." (PMID 35331302, 2022). "FOXA1 is a pioneer transcription factor that can open chromatin and facilitate the binding of other transcription factors, including ER, in breast cancer cell lines." (PMID 35353838, 2022). "Clinically, combining gene therapy of FOXA1 knockdown with ultrasound targeted microbubble destruction technology has been proved effective in the non-invasive therapy of breast cancer." (PMID 36292640, 2022). "Note the combined enrichment for FOXA1, ESR1, and GATA3 TFs close to the emCpGs; these 3 TFs have already been associated with DNA methylation patterns in estrogen receptor positive breast cancers." (PMID 35440061, 2022). "The experimental assessment of the effect of FOXA1 expression on DNA methylation in the MCF-7 breast cancer cell line revealed a limited number of FOXA1-bound regions with significant differential methylation." (PMID 35440061, 2022). "Based on the predicted results from the UALCAN database, promoter methylation levels of FOXA1 were lower in breast carcinoma compared to normal tissues." (PMID 36292640, 2022). "AP2γ, FOXA1, and ERα jointly target genes of the luminal phenotype during breast cancer progression." (PMID 35440541, 2022).
breast carcinoma (continued). "Subsequently, we analyzed the expression of FOXA1 using the Human Protein Atlas database and observed that FOXA1 was up-regulated in more than 70% of patients with breast cancer (n normal = 5, n tumor = 22)." (PMID 35359970, 2022). "“Androgen receptor driven transcription in molecular apocrine breast cancer is mediated by FoxA1” was the article with the highest betweenness centrality, also showing a high correlation between ARs and FOXA1 in molecular apocrine breast cancer." (PMID 35800434, 2022). "These interactions further support the in silico predictions for the importance of FOXA1 in driving local demethylation patterns in breast cancer." (PMID 35440061, 2022). "From the list of 13 emTFs, we experimentally investigated the role of FOXA1 in DNA demethylation in breast cancer." (PMID 35440061, 2022). "Recurrent alterations in cis-chromatin interactions were observed at loci encoding the pioneer factor FOXA1 (prostate cancer), the cell cycle gene CDK12 (breast cancer), and the RAB36 gene (leukemia)." (PMID 35902807, 2022). "In ER+ breast cancer cell lines, FOXA1 inhibits cell growth by inducing E-cadherin expression and suppressing ER pathway activity, which suggests that FOXA1 can be a favorable prognostic marker in human breast cancer." (PMID 35906698, 2022). "Suppression of POLR3G activates the expression of FOXA1 and androgen receptor, two key factors that are characteristic of luminal and molecular apocrine breast cancers in which they contribute to controlling hormone response and can be targeted for therapies." (PMID 36497214, 2022). "We then looked for FOXA1 and GATA3 binding sites in HCC1954 breast cancer cells by performing chromatin immunoprecipitation sequencing (ChIP-seq) using FOXA1 and GATA3 antibodies in two biological replicates each." (PMID 35331302, 2022). "In breast cancer, overexpression of FOXA1 and HER2 has already been demonstrated to be strongly associated with estrogen receptor (ER)-negative breast tumors." (PMID 35203384, 2022). "The interaction of FOXA1 with co-factors such as ESR1 and E2F1 enhanced the susceptibility of breast cancer." (PMID 36292640, 2022). "Collectively, our data indicate that FOXA1 expression is essential in promoting cellular plasticity across the basal/luminal spectrum which is mainly dictated by the EMT-TF SNAI1 in breast cancer cells." (PMID 36171192, 2022). "This novel chromatin opener is enriched at ER loci and cooperates with FOXA1 to drive endocrine therapy resistance in luminal breast cancer." (PMID 35774123, 2022). "In ER-mediated transcription, FOXA1 has also been shown to recruit MLL3 to promote H3K4me3 at ER binding sites in breast cancer cell lines." (PMID 35269520, 2022). "In conclusion, FOXA1 is a determinant of multidrug resistance and anchorage independence in breast cancer cells." (PMID 33417085, 2021). "While checkpoint inhibitors are effective in other tumor types, most breast cancers, especially those with elevated expression of FOXA1, are immunologically “cold,” precluding any benefit from the use of immune checkpoint inhibitors." (PMID 34680352, 2021). "Given that FOXA1 has been shown to function in response to proinflammatory signaling and endocrine resistance in breast cancer cells and in regulatory T cells, it will be critical to discriminate FOXA1-dependent, cell type-specific effects." (PMID 33980863, 2021). "The pioneering function of FOXA1 establishes estrogen-responsive transcriptomes in luminal breast cancer." (PMID 34680352, 2021). "Eight of the top 10 (and 12 of 14 overall) feature sets in the FOXA1 AKLIMATE model were directly related to breast cancer experiments under different conditions." (PMID 33861732, 2021). "One of the essential factors that dictate steroid NR signaling in breast cancer is the transcription factor, FOXA1." (PMID 34680352, 2021).